NLRP3 (NLR family pyrin domain containing 3)
Diseases named in the same sentence as NLRP3 in open-access papers (continued):
Sharing a sentence is not in itself a finding about the gene and the disease.
colitis (continued). "B. velezensis MZ09 alleviates DSS-induced colitis in piglets through multiple pathways, including gut microbiota remodeling, SCFAs–GPR43–STAT3 axis activation, and NLRP3 inflammasome-mediated pyroptosis suppression." (PMID 40883849, 2025). "WT161, an inhibitor of HDAC6, is confirmedto impede the activation of NLRP3 inflammasome by disrupting ASC spotformation and decreasing NLRP3 expression, mitigates intestinal damage,and suppresses intestinal inflammation in colitis models." (PMID 41210754, 2025). "Baicalein has been shown to attenuate TNBS-induced colitis by inhibiting the TLR4/MyD88 signaling cascade and inactivating the NLRP3 inflammasome." (PMID 40130239, 2025). "RRx-001has shown beneficial effects in NLRP3-driven inflammatory diseases such as lipopolysaccharide (LPS)-induced systemic inflammation, DSS-induced colitis and EAE in mice." (PMID 38421496, 2024). "Mechanically, the current study revealed that HDAC3 promotes the development of colitis in macrophages by positively regulating IFN-γ-induced expression of GBP5 and enhancing the activation of NLRP3 inflammasomes in GBP5-dependent manners." (PMID 38903915, 2024). "MSC-Ex alleviates colitis by increasing FXR in the colon, which binds to the NLRP3 inflammasome and inhibits the activation of inflammasome components." (PMID 39185411, 2024). "It has been demonstrated that GL-V9 triggers autophagy in macrophages via AMPK signaling, degrades the NLRP3 inflammasome, and attenuates DSS-induced colitis." (PMID 39684769, 2024). "In the model of colitis induced by dextran sulfate sodium (DSS), NLRP3 inflammasome emerges as a central regulator driving intestinal inflammation." (PMID 38584157, 2024). "For example, L-fucose inhibits macrophage M1 polarization, inactivates the NLRP3 inflammasome, and decreases the levels of TNF-α, IL-1β, and IL-6 in mice with DSS-induced colitis." (PMID 38596683, 2024). "Mao 547 also showed that HT supplementation ameliorated colon pathology and apoptosis, increased antioxidant capacity, and reduced expression of NLRP3 inflammasome components and pro-inflammatory cytokines in the DSS-induced colitis model." (PMID 39494333, 2024). "NLRP3 inflammasome activation and IL-1β release is a major pathology in the UC patients and also in the DSS-induced colitis model." (PMID 38417794, 2024). "In the study conducted by Wu and colleagues, they reported that the overexpression of miR-200c alleviated cell inflammation and pyroptosis related to the NLRP3 inflammasome and ameliorated DSS-induced murine colitis symptoms via NEK7 modulation." (PMID 39684769, 2024). "For example, in colitis-induced CRC mice, a high-cholesterol diet increased tumorigenesis through the mitochondrial ROS-mediated upregulation of the NLRP3 inflammasome." (PMID 39201713, 2024). "In an in vitro cellular model of dextran sulfate sodium (DSS)-induced colitis, the DUB OTU domain-containing protein 6A (OTUD6A) interacted with structural domains of the NLRP3 inflammasomes inducing their deubiquitination." (PMID 38193803, 2024). "We aimed to investigate the anti-colitis efficacy of CSCC and explore the mechanism by which GPR43 inhibits the NLRP3/STAT3 signaling pathway, thereby mediating the protective effects of CSCC on the intestinal barrier." (PMID 39329121, 2024). "As a result, administering B. vulgatus to rodents with colitis improved survival by mediating CD82 expression and activating NLRP3." (PMID 38892354, 2024). "RT-qPCR analysis results showed that EIF treatment significantly reduced the expression of inflammasome component genes (NLRP3, caspase-1, and ASC) and IL-1β in the colon tissue of DSS-induced colitis mice." (PMID 39408295, 2024). "Further, in an acetic acid-induced colitis model and caco-2 colon epithelial cells, cyclooxygenase-2 (COX-2) inhibitor (mangiferin) prevents activation of NLRP3 and expression of inflammatory markers such as IL-1β, TNF-α, IL-16, and IFN-γ." (PMID 39769450, 2024).
colitis (continued). "TRIM31 can inhibit NLRP3 activation by promoting the NLRP3 inflammasome polyubiquitination and proteasome degradation, thereby alleviating DSS-induced colitis." (PMID 39420190, 2024). "In DSS-induced colitis mice, indole-3-acetic acid can also regulate the AhR/NRF2/NLRP3 pathway to alleviate intestinal inflammation and barrier function damage." (PMID 39334766, 2024). "Inflammatory cytokines and expression of M1 polarization markers, p47phox, NLRP3, Caspase-1 p20 were also increased in macrophages isolated from TNBS-induced colitis mice." (PMID 38796413, 2024). "In the current study, we found HDAC3 promoting IFN-γ induced expression of GBP5, which in turn, potentiated the activation of NLRP3 inflammasomes and aggravated the disease severity of DSS-induced colitis." (PMID 38903915, 2024). "The reduction in expression level of NLRP3 and its activity was further validated by measuring IL-1β, IL-13, MPO, and NO in colitis-induced mouse model." (PMID 37902927, 2024). "Recent studies reported that MNS suppresses NLRP3 inflammasome and decreased dextran sulfate sodium (DSS)-induced colitis in mice and fungal pathogen-induced airway inflammation." (PMID 38421496, 2024). "The changes in the expression of inflammasome component genes (NLRP3, caspase-1, ASC) and IL-1β in the colon tissue of DSS-induced colitis mice following EIF treatment were examined using RT-qPCR." (PMID 39408295, 2024). "Our data exhibited NLRP3 activation after DSS-induced colitis; however, ECE pretreatment reduced NLRP3 expression and further suppressed NF-κB activation, a prerequisite for NLRP3 activation." (PMID 38138587, 2023). "The MC-LR facilitated the level of NLRP3 in the colonic tissue of colitis mice, suggesting that the digestive cytotoxicity of MC-LR in IBD is related to the priming of the NLRP3 inflammasome." (PMID 37505716, 2023). "It has been shown to reduce the inflammatory response in colitis mice by inhibiting the Toll-like receptor 4 (TLR4)/Nuclear factor kappa B (NF-κB) pathway and NLR-family-pyrin-domain-containing 3 (NLRP3) inflammasome activation." (PMID 37444374, 2023). "The results showed that the mRNA expression levels of NLRP3, GSDMD and NF-κB were highly expressed in the colon tissues of DSS-induced colitis and significantly decreased in the T.s intervention groups." (PMID 37580819, 2023). "DSS-induced mice treated with Sinapic acid had significantly decreased levels of NLRP3, IL-1b, ASC, and Caspase-1, which improved symptoms of colitis.." (PMID 37849728, 2023). "In a rat model, inhibition of the NLRP3 inflammasome by INF39, an acrylate derivative and irreversible inhibitor of NLRP3, decreased IL-1β secretion and alleviated colitis induced by 2,4-dinitrobenzenesulfinic acid in rats." (PMID 36669831, 2023). "The activation of NLRP3 is involved in the progression of UC and its inhibition is known to ameliorate DSS-induced colitis." (PMID 36843930, 2023). "The results indicated that GA significantly downregulated the NLRP3 expression, consistent with its inflammatory intervention in DSS-induced colitis." (PMID 36762118, 2023). "Specifically, chlorogenic acid alleviated colitis through reducing PKM2-dependent glycolysis and inhibiting NLRP3 activation that shift macrophage polarization." (PMID 37813835, 2023). "Baicalein suppressed TNBS-induced colitis, at least in part, by inhibiting TLR4/MyD88 signaling and inactivating the NLRP3 inflammasome." (PMID 37849728, 2023). "Palmatine protected mice against DSS-induced colitis by facilitating PINK1/Parkin-driven mitophagy and thus inactivating NLRP3 inflammasomes in macrophage." (PMID 36647064, 2023). "For example, cardamonin, a natural flavone isolated from Alpinia katsumadai Hayata, attenuates mice colitis by activating the AhR/Nrf2/NQO1 pathway and inhibiting the activation of the NLRP3 inflammasome." (PMID 37370025, 2023). "Dioscin can be effective in inhibiting DSS-induced colitis NF-κB, MAPK signaling, and NLRP3 pathway." (PMID 37849728, 2023).
colitis (continued). "Next, we investigated the effects of the small-molecule inhibitors targeting NLRP3 (MCC950) and Caspase-8 (Z-IETD-FMK) on bacterial composition in fecal samples collected on day 0 and 12 from IL10−/− mice with colitis induced by AIEC/piroxicam." (PMID 36656595, 2023). "Overall, this study empirically demonstrated that BDX-01 alleviates DSS-induced colitis by activating colonic FXR and inhibiting the NLRP3 inflammasome signaling pathway." (PMID 37292154, 2023). "In mouse colitis model, MCC950 was demonstrated to act on NLRP3 by inhibiting ASC oligomerization and caspase-1 dependent activation of IL-1β and IL-18, and reducing the levels of pro-inflammatory cytokines." (PMID 37681916, 2023). "VAD mice demonstrated severe experimental colitis and increased expression of inflammasome-related proteins (caspase-11, GSDMD, NLRP3, ASC, caspase-1, IL-1β, and IL-18) in the colonic LP." (PMID 37240022, 2023). "In this study, it was found that Lib M can effectively alleviate the symptoms of colitis in the DSS-induced UC mouse model, indicating that Lib M has a reasonable therapeutic prospect as a UC drug targeting NLRP3." (PMID 37849728, 2023). "APS can also downregulate the expression of NLRP3, caspase-1, and ASC in colon tissue, prevent the activation of the NLRP3 inflammasome, thereby reducing the expression of IL-18 and IL-1β and alleviating DSS-induced colon inflammation." (PMID 37849728, 2023). "Therefore, NLRP3-mediated IL-18 secretion promoted differentiation of intestinal epithelial cells, maintained intestinal epithelial integrity and reduced intestinal epithelial cell proliferation during colitis remission, protecting cells from malignant transformation." (PMID 37081882, 2023). "In this study, we focus on the effect of GA on experimental colitis induced by dextran sulfate sodium (DSS) in mice and its influence on the NLRP3 inflammasome." (PMID 36762118, 2023). "It has been reported that DCA triggers NLRP3 inflammasome activation and aggravates DSS-induced colitis in mice, and high fat diets increase the level of fecal DCA, which contributes to colonic inflammation." (PMID 37504267, 2023). "Mice treated with SCH experienced significant weight gain, effectively alleviating the severity of colitis, and decreasing the levels of inflammatory factors such as TNF-α, IL-1β, IL-18, IL-6, and other related proteins (NLRP3, Caspase-1, SGK1) in UC mice." (PMID 37674245, 2023). "Using caspase-1/11-/-, NLRP3-/-, NLRC4-/-, IL18-/-, and IL22-/- mice, we showed that KLPJ-mediated colitis occurred through activation of caspase-11, and was dependent on IL18 and partly on IL22." (PMID 36436756, 2023). "Loading TNF-α with GELNs can downregulate NLRP3, caspase-1, IL-1β, TNF-α, IL-6 and IL-1b, upregulate anti-inflammatory substances such as IL-10 and IL-22 in colon tissue of DSS-induced colitis mice." (PMID 37033644, 2023). "Roseburia intestinalis, a butyrate−producing bacterium, -derived flagellin was demonstrated to inhibit the activation of NLRP3/caspase-1/GSDMD signaling-triggered pyroptosis in macrophages by targeting miR−223−3p and ameliorate colitis." (PMID 36505474, 2022). "SPC mice had lower NLRP3 mRNA levels than DSS-treated control mice, demonstrating that SPC is able to prevent increased pro-inflammatory signaling and thereby moderate colitis severity." (PMID 35276849, 2022). "In this study, we tested the inhibition potential of the ethanolic extract of L. cubeba leaves against the NLRP3 inflammasome in macrophages and in a mouse model of dextran sulfate sodium (DSS)-induced colitis." (PMID 35967819, 2022). "Results demonstrated, for the first time, that SUCNR1 mediated NLRP3 priming in both intestinal epithelial cells and a murine model of DSS-colitis, and that this receptor correlated with inflammasome markers in human UC." (PMID 35327334, 2022).
colitis (continued). "This pathway and associated inflammatory markers could be relevant in colitis as NLRP3 inflammasome activity (critical for caspase 1-dependent release of IL-1β and IL-18) in the CNS has been implicated in the exacerbation of neuroinflammation by DSS-induced colitis in aging mice." (PMID 34983592, 2022). "This induced the defective activation of NLRP3 inflammasomes, making mice more vulnerable to dextran sulfate sodium (DSS)-induced colitis." (PMID 36275694, 2022). "The mRNA expressions of NLRP3, ASC, caspase-1, GSDMD, IL-18, and HMGB1 were shown to increase in different extents in colitis tissues than in control tissues, whereas SM934 treatment decreased the expression of these genes." (PMID 36120344, 2022). "ADP, a danger signal released during colonic injury from IECs, activates NLRP3 inflammasomes via P2Y1 receptors and promotes phosphorylation of NLRP3 inflammasomes component ASC to increase IL-1β production, thereby worsening DSS-induced colitis in mice." (PMID 36590401, 2022). "In dextran sulphate sodium (DSS)-induced colitis, it was shown that SNAI1 augmented the effects of MIST1 on the inflammasome protein NLRP3, promoting inflammation." (PMID 35484353, 2022). "Corylin significantly reduced Ifnγ, Tnf-α, Il-6, Il-1β, Nlrp3, Asc, Pannexin, and Pro-caspase 1 mRNA expression and protein levels in DSS-induced colitis mice." (PMID 35269806, 2022). "Staphylococcus aureus has been shown to suppress colitis and related CRC by activating Nlrp3, and Bacillus fragilis inhibits the secretion of IL-1β and IL-18 regulated by Nlrp3." (PMID 35954484, 2022). "Accumulating evidence also shows a beneficial role for DMF in experimental colitis; this may be due to activation of Nrf2, which results in decreased mitochondrial ROS generation and mitochondrial DNA release, followed by suppression of NLRP3 inflammasome activation." (PMID 35269986, 2022). "In our previous study, we found that the histone acetyltransferase inhibitor C646 inhibits NLRP3 inflammasome activity and exerts anti-inflammatory effects in dextran sulfate sodium (DSS)-induced colitis mice by targeting the NLRP3 inflammasome." (PMID 35330829, 2022). "Recent studies revealthat PAP-1 (a Kv1.3 channel-specific blocker) downregulates Kv1.3 expression inmacrophages in mice with colitis and inhibits macrophage activation.Moreover, PAP-1 effectively inhibits the expression of NLRP3,ASC, caspase-1p20 and IL-1β." (PMID 39076616, 2022). "Curcumin potently inhibited NLRP3 inflammasome activation to alleviate colitis in a DSS-induced murine model, and the therapeutic outcome was partially limited following the use of MCC950 (a specific NLRP3 blocker)." (PMID 36145301, 2022). "This molecule has demonstrated an inhibitory effect against the NLRP3 signaling pathway, decreasing the protein levels of NLRP3, ASC, caspase-1 p45, and caspase-1 p20 in the colon tissue of BALB/c mice with induced colitis." (PMID 35276849, 2022). "Previous studies showed that the induction of apoptosis was required for the activation of the NLRP3 inflammasome in the signaling cascade, but the concrete contribution of NLRP3 inflammasome activation to DSS−induced colitis was still elusive." (PMID 36290717, 2022). "Some studies in NLRP3 knock-out mice showed protection in TNBS, DSS and oxazolone models of colitis, whereas others have described a detrimental or worse colitis in the same knock-out mice." (PMID 35327334, 2022). "Colorectal administration of DCA enhanced IL1β levels in murine colonic tissue and exacerbated DSS colitis, which was ameliorated following S1PR2 inhibition, NLRP3 inhibition, or macrophage depletion." (PMID 35185922, 2022). "In this study, we found that WT161 exerts a protective role in a colitis model, blocks NLRP3 inflammasome activation, disrupts ASC speck formation, and decreases NLRP3 expression." (PMID 35330829, 2022).
colitis (continued). "In this study, we are the first to show that the ethanolic extract of L. cubeba leaves exerts NLRP3 inflammasome inhibitory activity in macrophages and ameliorates DSS-induced colitis in mice." (PMID 35967819, 2022). "Ginsenoside Rd ameliorated colitis by inducing p62-driven mitophagy-mediated NLRP3 inflammasome inactivation and upregulating of AMPK/ULK1 signaling pathway in DSS-induced murine colitis model." (PMID 35454101, 2022). "DSS is not only a well-studied induction model for colitis, but DSS can also induce caspase-1 cleavage via activation of the NLRP3 inflammasome." (PMID 35246034, 2022). "Coinciding with the results of the current study, the crosstalk between TLR4, NLRP3 inflammasome, and NF-κB signaling was proven to be a key regulator of the pathophysiology of DSS-induced colitis." (PMID 35631426, 2022). "Taken together, these results indicate that echinatin attenuates NLRP3 inflammasome activation and reverses the pathological process of DSS-induced colitis." (PMID 33350984, 2021). "Both, aggravated as well as less severe course of disease have been reported for Nlrp3−/− mice during acute DSS and TNBS colitis." (PMID 34344313, 2021). "Patchouli alcohol, a main active compound of traditional Chinese herb patchouli, showed improved therapeutic efficacy in a DSS-induced colitis by inhibiting MAPK/NF-κB pathway and NLRP3 inflammasome." (PMID 34299310, 2021). "LEP also plays a role in inhibiting NLRP3 inflammasome activation, ER stress, and oxidative/nitrosative stress in DSS-induced colitis." (PMID 33808793, 2021). "In this study, the expression of NLRP3, ASC, and Cleaved caspase-1 was increased while the expression of CLDN1, OCLN, and ZO-1 was decreased in colon tissues of colitis mice, which were reversed by YST to near normal levels." (PMID 34055024, 2021). "Studies have shown that Astragalus polysaccharide reduces NLRP3 inflammasome activation and IL-1β and IL-18 levels in DSS-induced colitis." (PMID 34462641, 2021). "Studies also proposed that SCFAs activated the NLR family pyrin domain containing 3 (NLRP3) inflammasome, thereby upregulating the secretion of IL-18, which is protective for epithelial integrity, and ameliorating DSS-induced colitis." (PMID 34439208, 2021). "This is accompanied by lower production of colonic inflammatory cytokines (i.e., Nlrp3, IL-1β, IL-6, Tnf-α and Ccl2, all these are REV-ERBα target genes) in ZT10-treated than in ZT2-treated colitis mice." (PMID 34393786, 2021). "This was accompanied by lower production of colonic inflammatory cytokines (i.e., Nlrp3, IL-1β, IL-6, Tnf-α and Ccl2, REV-ERBα target genes) in colitis mice dosed at ZT10." (PMID 34393786, 2021). "When taken together, these findings showed that Xi Lei San significantly inhibited the activity of NLRP3 inflammasomes and autophagy in the DSS-induced colitis model rats." (PMID 33967625, 2021). "Their data showed that R.I flagellin treatment ameliorated colitis induced by DSS, inhibited NLRP3 inflammasome activation in the colon, and reduced Gasdermin D-mediated pyroptosis by regulating the expression of miR-223-3p." (PMID 33808793, 2021). "The number of cortical microglia was also lower in DSS-fed NLRP3 KO mice than DSS-fed WT mice (P < 0.001), suggesting the suppression of NLRP3 inflammasome activity protected against colitis-induced neuroinflammation and neurodegeneration." (PMID 34229722, 2021). "Conversely, the bacterial metabolite hydrogen sulphide (H2S) has been shown to inhibit NLRP3 inflammasome and IL‐1β secretion in BMDMs and in dextran sulphate sodium (DSS)‐induced colitis colons via reduced ROS and Nrf2 activation." (PMID 33682108, 2021). "To determine the immune regulatory mechanism of mEVs in DSS-induced colitis model, we examined the expression of several crucial regulators in the TLR4-NF-κB and NLRP3 signaling pathways by western blotting, immunohistochemistry and RT-PCR analysis." (PMID 34373759, 2021).